PITPNA-AS1 (PITPNA antisense RNA 1)
Gene: Long non-coding RNA gene on chromosome 17 (1,516,815 to 1,518,106, forward strand). Ensembl gene ENSG00000236618.
Diseases named in the same sentence as PITPNA-AS1 in open-access papers:
PITPNA-AS1 is named in the same sentence as 1 disease in open-access papers, as found by Europe PMC text mining. Sharing a sentence is not in itself a finding about the gene and the disease. The quoted sentences say what the papers report.
cancer (1 paper, 2021). A tumor composed of atypical neoplastic, often pleomorphic cells that invade other tissues. "LncRNA PITPNA antisense RNA 1 (PITPNA-AS1) has been explored in some cancers, whereas its function and molecular mechanism in TNBC remain unclear." (PMID 34353336, 2021).